SIRT5 (sirtuin 5)
Diseases named in the same sentence as SIRT5 in open-access papers (continued):
Sharing a sentence is not in itself a finding about the gene and the disease.
cancer (continued). "To demonstrate that SIRT5 controls autophagic flux in cancer cells, we determined the LC3‐II protein level, a marker of the autophagic flux." (PMID 30443978, 2019). "Depending on the type of cancer SIRT5 has been reported to act as both oncogene and tumor suppressor." (PMID 31608237, 2019). "Our in vivo and in vitro data indicate that the specific deacetylation of LDHB by SIRT5 is essential for cancer development." (PMID 30443978, 2019). "After the cell proliferation advantage afforded by SIRT5‐mediated LDHB deacetylation to cancer cells in vitro was verified, we performed xenograft studies in vivo." (PMID 30443978, 2019). "The post-translational mechanism, by which LDHB is regulated during autophagy in cancer cells, implicates sirtuin 5 (SIRT5)." (PMID 31035592, 2019). "One of the post-translational mechanisms of LDHB regulation in cancer cell autophagy is via binding with protein Sirtuin 5 (SIRT5)." (PMID 31146503, 2019). "As expected, supplementation of cells with DM α-KG (1 mM) rescued the decreased proliferation in cancer cells after SIRT5 silencing, and also reduced the level of the apoptosis marker, cleaved PARP, which was induced by SIRT5 knockdown." (PMID 29416026, 2018). "We also showed that GLUD1 is critical and sufficient for SIRT5-mediated cancer progression, both in vivo and in vitro." (PMID 29416026, 2018). "Consistently, our in vitro and in vivo results showed that GLUD1, an enzyme involved in glutaminolysis, is critical for SIRT5-driven cancer progression." (PMID 29416026, 2018). "The SIRT5 protein level in paired normal colon mucosa and cancer tissues was determined by immunofluorescence histochemistry." (PMID 29416026, 2018). "In contrast, the SIRT5 level was lower in cancer tissue sections than in adjacent normal tissue sections." (PMID 28004755, 2016). "SIRT5, a mitochondrial sirtuin, is present both inside the mitochondria and within the cytosol and nucleus.SIRT5 has been reported to facilitate cancer cell growth and drug resistance in non-small cell lung cancer." (PMID 26658802, 2015). "This differential sensitivity positions SIRT5 as a promising therapeutic target in cancer." (PMID 41107644, 2025). "By modulating the succinylation state of proteins, SIRT5 can influence metabolic pathways, transcriptional activities, and other cellular processes, thereby playing a significant role in health and disease, including cancer development and progression." (PMID 39944690, 2025). "In addition to AML, SIRT5 overexpression has been reported in liver cancer, colorectal cancer, and other cancers and is often correlated with poor prognosis, suggesting that many tumors benefit from suppressing malonylation." (PMID 41107644, 2025). "Thus, elevated SIRT5 expression has been observed in various cancers and correlates with poor patient prognosis." (PMID 39944690, 2025). "Considering the important and interconnected role of glutamine, SIRT3 and SIRT5 for cancer growth and progression, our hypothesis is that a simultaneous modulation of SIRT3 and SIRT5 could represent a valid anti-tumoral strategy." (PMID 41599625, 2025). "The emerging therapeutic view is that SIRT5 inhibition or malonyl-CoA modulation could selectively target the metabolic fragility of cancer cells, a strategy strengthened by consistent observations across metabolic, inflammatory, renal, and cardiac diseases." (PMID 41107644, 2025). "With its diverse range of functions, SIRT5 presents a potential target for developing agonists or inhibitors that can serve as effective therapeutic agents for an array of illnesses, including cancer, cardiovascular disease, and neurodegeneration." (PMID 39979670, 2025). "Low SIRT5 levels could lead to increased levels of ROS and other metabolic disturbances, potentially promoting cancer progression." (PMID 40710366, 2025).
cancer (continued). "Similarly, SIRT5, known for its involvement in cellular stress responses and cancer metabolism, was upregulated, aligning with its reported functions in other cancers." (PMID 40128844, 2025). "Understanding the impact of NAD+ levels on SIRT5 activity can provide insights into the enzyme’s role in cellular physiology and offer potential intervention strategies for related diseases, including cancer." (PMID 39944690, 2025). "Therefore, it is necessary to develop selective modulators of SIRT5 to provide new avenues for the treatment of diseases, especially cancer." (PMID 39979670, 2025). "SIRT5 regulatory pathways may provide new insights into metabolic reprogramming of cancer cells and may provide targets for future anticancer treatment." (PMID 40865948, 2025). "The role of SIRT5 in diseases, especially cancer, is related to various mechanisms such as metabolism, apoptosis, and redox, and has become an important target for clinical treatment of cancer research." (PMID 39979670, 2025). "Hence, there is a great potential for treating cancer and other illnesses by elucidating the interrelationship between SIRT5 and metabolism." (PMID 39979670, 2025). "SIRT5 has complex functions, and in the context of cancer, it exhibits a contradictory role." (PMID 39979670, 2025). "Additionally, SIRT5 modulators are being investigated for their potential for metabolic and age-related diseases, such as T2D, AD, and cancer." (PMID 40799515, 2025). "Notably, SIRT5 can also promote cancer development by regulating proliferation and migration through deacetylation of its substrates." (PMID 39479446, 2024). "High levels of SIRT5 activity have been linked to the desuccinylation and resultant decreased activity of succinate dehydrogenase (SDH), which is associated with increased cancer cell proliferation." (PMID 38374872, 2024). "MC3138 activates SIRT5, which decreases the levels of metabolites in the glutamine, glutathione, and pyrimidine pathways, and triggers mitochondrial autophagy, which increases total and mitochondrial ROS to inhibit cancer cell proliferation." (PMID 39479446, 2024). "Mitochondrial sirtuins, (Sirtuin) SIRT3, SIRT4, and SIRT5, play crucial roles in cancer metabolism." (PMID 38331199, 2024). "Indeed, SIRT5 blocks the cell cycle of cancer cells at the G1/S phase by negatively modulating cyclin dependent kinase 2 (CDK2) and inhibiting glycolysis." (PMID 36980194, 2023). "On the other hand, SIRT5 depletion reduces ROS levels and promotes the growth of cancer cells." (PMID 36980194, 2023). "SIRT5 is involved in folic acid metabolism, which promotes the growth of cancer cells." (PMID 37175631, 2023). "Recently, SIRT5 was reported to be a downstream target of several microRNAs, including miR-299-3p, miR-19b, and miR-3677-3p, which regulate the proliferation, migration, and invasion of cancer cells." (PMID 35278714, 2023). "Considering the interconnected roles of GLS, SIRT5 and Pi in cancer growth, our hypothesis is that activation of SIRT5 and reduction in Pi could represent a valid antitumoral strategy." (PMID 37627630, 2023). "Additionally, SIRT5 modulates the activity of PDC and SDH, which are associated with cancer cell metabolism reprogramming and neoplasia." (PMID 37175631, 2023). "Indeed, SIRT5 is downregulated in murine pancreatic tumors and human PDAC tissues, and its hypoexpression has been linked to cancer development and poor prognosis." (PMID 36980194, 2023).
cancer (continued). "Considering the important and interconnected role of glutamine, SIRT5 and inorganic phosphate (Pi) in cancer growth and progression, our hypothesis is that activation of SIRT5 and reduction in Pi could represent a valid antitumoral strategy." (PMID 37627630, 2023). "This indicates that SIRT5‐mediated succinylation regulation is mediated not only by its direct binding to the desuccinylation substrate but also by the regulation of SUCLG2 expression to influence overall succinylation in cancer cells." (PMID 37904651, 2023). "The combination of SIRT5 activation with gemcitabine could be a therapeutic strategy against this type of cancer." (PMID 37627630, 2023). "Like other SIRTs, the role of SIRT5 in cancer is rather controversial." (PMID 36980194, 2023). "Hence, GOT1-mediated SIRT5 suppression results in decreased cancer cell detoxification systems, an increase in ROS, and decreased proliferation." (PMID 36980194, 2023). "Notably, hypersuccinylation of SHMT2 caused by SIRT5 KO in osteosarcoma (U2OS) and CRC (HCT116) cells or expression of succinylation mimic mutant (K280E) significantly reduced cancer cell growth both in vitro and in vivo." (PMID 36980194, 2023). "Because Sirt5 supports glutamine metabolism in cancer cells by protecting GAC from degradation, we examined whether Sirt5 expression was increased in a manner like ATF4 in response to metabolic stress." (PMID 35963851, 2022). "SIRT5 regulates cell migration and invasion in several cancer cells." (PMID 36581622, 2022). "Indeed, SIRT5-dependent GLS stabilization is the main mechanism by which SIRT5 promotes cancer cell growth and survival." (PMID 35897717, 2022). "Another protein, Sirtuin 5 (SIRT5), belonging to the Sirtuin family of proteins (Sirt1–7), is involved in the regulation of multiple cellular processes, including glycolysis, fatty acid oxidation, nitrogen metabolism and drug resistance in cancer cells." (PMID 35453348, 2022). "Potent inhibitors of SIRT5 are in development, and SIRT5 is a potential target against cancer." (PMID 36095012, 2022). "SIRT5 inhibitors (sirtuin-inhibiting compounds, STICs) have been studied for their potential role in the treatment of metabolic disorders, neurodegenerative pathologies, cardiovascular diseases, and cancer." (PMID 35889322, 2022). "SIRT2 and SIRT5 inhibitors showed rather consistent and promising effect in treating cancers." (PMID 34650436, 2021). "While our data manifest the importance of SIRT5 in T cell activation and antitumor functions, many questions still remain, including the substrate of SIRT5, PTMs involved, the effects of SIRT5 on other T cell fates, and the broader implications for antitumor functions and cancer immunotherapy." (PMID 32953892, 2020). "Previous studies have claimed that SIRT5 differential expression could lead to decreased cell growth, endoplasmic reticulum stress (ER stress), senility and apoptosis in various cancers." (PMID 32596968, 2020). "Overexpression of SIRT5 promoted cancer cell growth and drug resistance." (PMID 32158696, 2020). "Previous studies have claimed that SIRT5 differential expression could lead to suppressed cellular growth, endoplasmic reticulum stress (ER stress), senility and apoptosis in various cancers." (PMID 32596968, 2020). "In addition, certain aspects of cancer biology, such as stress responses, apoptosis, and autophagy, can be regulated by SIRT5." (PMID 31456942, 2019). "Janus-faced roles of SIRT5 in cancer have also been described." (PMID 31456942, 2019). "SIRT5-induced LDHB deacetylation hyperactivates autophagy and targeting SIRT5/LDHB pathway could be highly useful in LDHB positive cancers." (PMID 31146503, 2019). "However, few studies have discussed the mechanism of SIRT5-catalysed demalonylation in the progression of cancer cells." (PMID 31817470, 2019). "Finally, malonylation levels or SIRT5 expression might serve as biomarkers for stratifying cancers that respond to these metabolic interventions." (PMID 41107644, 2025).
cancer (continued). "However, the functional consequences of these post‐translational modifications are not clear yet, and many data have been obtained from model systems investigating pathologic conditions such as cancer or through knockout models of SIRT5 that force the cell towards hyperacylation." (PMID 40172090, 2025). "The ongoing elucidation of SIRT5’s functions and mechanisms may pave the way for novel therapeutic approaches that target metabolic pathways in cancer treatment, potentially improving outcomes for patients with malignancies characterized by dysregulated metabolic processes." (PMID 39944690, 2025). "Additionally, exploring the role of SIRT5 in immune modulation could open new avenues for immunotherapy, particularly in cancers that exhibit resistance to current therapies." (PMID 39944690, 2025). "However, SIRT5 is able to reverse this succinylation to promote cancer progression." (PMID 40867281, 2025). "Indeed, a recent research sheds light on Sirt5’s involvement in cancer cell development." (PMID 38605962, 2024). "We observed that SIRT5 expression is strongly correlated with mitochondrial metabolism, mitochondrial dynamics and surveillance, and oxidative phosphorylation-related pathways, which is consistent with previous reports showing its aberrant regulation of lysine succinylation in various cancers." (PMID 39201811, 2024). "SIRT5, by modulating key metabolic enzymes, could be involved in cancer." (PMID 36095012, 2022). "However, the relationship between SIRT5 and cancer metabolism in ccRCC remains elusive." (PMID 34930316, 2021). "Efforts are currently devoted to the generation of SIRT5 inhibitors such as thiosuccinyl peptides, cyclic pentapeptide harboring a central N(ε)-carboxyethyl-thiocarbamoyl-lysine residue and 3-arylthiosuccinylated and 3-benzylthiosuccinylated peptide derivatives for specific cancer types." (PMID 30515162, 2018). "Elevated SIRT5 expression has been observed in RCC cells and tissues, and SIRT5 knockout inhibits cancer cell proliferation." (PMID 39944690, 2025). "Studies have shown that SIRT5 is highly expressed in non-small cell lung cancer (NSCLC), and inhibition of SUN2 promotes cancer cell proliferation." (PMID 39979670, 2025). "Recent studies illustrate that desuccinylase (e.g., SIRT5 and SIRT7) and succinyltransferase (e.g., KAT2A, CPT1A, HAT1, and alpha-KGDH) expression and malfunction are strongly related to immune escape of cancer." (PMID 40865948, 2025). "SIRT5 also targets lactate dehydrogenase (LDHA), a critical enzyme in glycolysis that is frequently upregulated and hyper-succinylated in cancer cells." (PMID 41304967, 2025). "Conversely, silencing SIRT5 leads to SDH hyper‐succinylation and reactivation, thereby inhibiting cancer cell growth." (PMID 38374872, 2024). "SIRT5 is primarily targeted towards succinyl-lysine residues, impacting key metabolic pathways like the TCA cycle and amino acid degradation crucial for cancer cell proliferation." (PMID 38773972, 2024). "Additionally, SIRT5 can be involved in the regulation of substance metabolism, apoptosis, inflammatory reaction and other life activities through deacetylation, desucrylation, desmalonylation and deglutaranylation activities, and is closely related to the occurrence and development of cancer." (PMID 38773972, 2024). "The relationship between SIRT5 and GLUD1 in cancer metabolism, particularly in CRC, is of significant interest." (PMID 38773972, 2024). "SIRT1 helps cancer cells survive chemotherapy, SIRT2 inhibits cell growth, and SIRT3 controls mitochondrial health, while SIRT4, SIRT5, SIRT6, and SIRT7 each influence metabolism, angiogenesis, and metastasis." (PMID 39682281, 2024). "Both desuccinylation by SIRT5 and succinylation by succinyl-transferase should be considered for the potential role of LDHA succinylation as a key regulator in promoting cancer progression." (PMID 35278714, 2023).
cancer (continued). "In contrast to the decrease in the protein expression of SIRT5, protein expression of SIRT2 was increased in aggressive cancer cells." (PMID 35278714, 2023). "In order to better understand the role of GLS1 in cancer cells as well as the connection between GLS1 and SIRT5, we generated GLS1-silenced clones of MDA-MB-231 and CAL-62 cells." (PMID 37627630, 2023). "In line with this, SIRT5 KO or LDHB KD reduced CRC cell growth, and cancer cells overexpressing wild-type LDHB expanded more quickly than those overexpressing LDHB-K329Q." (PMID 36980194, 2023). "Our results confirm this finding, since by activating SIRT5 with MC3138, a relevant decrease in mitophagy is observed, which also reduces cancer cell vitality and proliferative capacity." (PMID 37627630, 2023). "SIRT5 also desuccinylates and activates SHMT2 to promote one-carbon metabolism and potential histone methylation in cancer cells." (PMID 36993975, 2023). "SIRT5 is a Class III HDAC that is involved in oxidative stress or metabolic homeostasis related to aging, degeneration, or cancer." (PMID 36172179, 2022). "Additionally, since increases in Sirt5 occurred when cancer cells were prevented from undergoing glutaminolysis, we tested whether increases in Sirt5 expression accompanying these stresses could be suppressed by supplementation with DM-αKG and found that to be the case." (PMID 35963851, 2022). "Roles for other sirtuin enzymes, such as sirtuin 5 (SIRT5), a desuccinylase and demalonylase enzyme, have been described in cancer cell proliferation, and thus are putative regulators of muscle regeneration." (PMID 34335302, 2021). "In this study, we performed a comprehensive pan-cancer analysis on four well-known succinylation regulators (CPT1A, KAT2A, SIRT5, and SIRT7)." (PMID 33681201, 2021). "There is only one SIRT5 selective inhibitor, DK1-04e, that showed promising effect in cellular and animal cancer studies." (PMID 34650436, 2021). "Thus, the promotion of autophagy by SIRT5 via LDHB suggested that they might affect cancer growth." (PMID 30443978, 2019). "Moreover, the succinyl modification of its K346 site can also be removed by SIRT5, leading to an enhancement of ME2 enzyme activity, which in turn promotes mitochondrial respiration and cancer cell proliferation." (PMID 40867281, 2025). "Increased cancer cell proliferation has been connected with desuccinylation and a consequent decrease in succinate dehydrogenase (SDH) activity, which is correlated with high levels of SIRT5 activity." (PMID 40581650, 2025). "A modulator of SIRT5 and SIRT7 has been developed to intervene in cancer, with promising results." (PMID 40867281, 2025). "It has been reported that SIRT5 deacetylation has both positive and negative effects on cancer regulation." (PMID 39979670, 2025). "Anchorage-independent growth leads to an increase in reactive oxygen species (ROS), and the presence of SIRT5 leads to the desuccinylation of isocitrate dehydrogenase (IDH2), a key enzyme in the antioxidant response, which attenuates ROS and promotes cancer cell growth." (PMID 40867281, 2025). "Its overall increase (such as when SIRT5 is absent) tends to impair the metabolic flexibility and growth of cancer cells, a suppressive effect that researchers are trying to harness for therapy." (PMID 41107644, 2025). "Sirt5, a NAD-dependent desuccinylase, fosters cancer cell survival during metabolic stress." (PMID 40598593, 2025). "Currently, only SIRT5 modulators have been reported for potential cancer therapy, and none have progressed to clinical trials." (PMID 38773972, 2024). "Since ammonia can trigger both mitophagy and autophagy in cancer cells, SIRT5-mediated suppression of GLS could circumvent this defense mechanism, pointing to an oncosuppressor function for SIRT5 in this setting." (PMID 36980194, 2023).